PARP1 (poly(ADP-ribose) polymerase 1)
Diseases named in the same sentence as PARP1 in open-access papers (continued):
Sharing a sentence is not in itself a finding about the gene and the disease.
Hyperglycemia (continued). "In a previous study, using a neonatal rat model, we have demonstrated that recurrent episodes of hypoinsulinemic hyperglycemia upregulate poly(ADP-ribose) polymerase-1 (PARP-1) expression in the cerebral cortex, likely due to oxidative stress." (PMID 29544513, 2018). "Meanwhile, hyperglycemia increased the mRNA and protein expression of ICAM-1 and iNOS, while PARP-1 deletion reduced hyperglycemia-induced ICAM and iNOS expression." (PMID 27027354, 2016). "Hyperglycemia, angiotensin II (Ang II), and oxidized low-density lipoprotein activate PARP1 in vascular endothelial cells (ECs), with attendant increase in oxidative and inflammatory stresses." (PMID 26986624, 2016). "With newly developed anti-phospho-PARP1 antibody, we address these questions with emphasis on improved endothelial functions by hyperglycemia and hypertension treatment." (PMID 26986624, 2016). "In vivo, hyperglycemia increased the protein expression of nitrotyrosine and PARP-1 as well as PARP-1 activity." (PMID 27027354, 2016). "It has been demonstrated that PARP-1 can be activated by high glucose or hyperglycemia in several cell lines, such as endothelial cells and umbilical endothelial cells." (PMID 27027354, 2016). "Interestingly, the researchers concluded that hyperglycemia silences TFPI-2 via PARP1-mediated TFPI-2 promoter methylation." (PMID 39153052, 2024). "In addition, hyperglycemia enhances NF-κB signaling pathway—increased NF-κB and its co-activator PARP1 expression—and also promotes the overexpression of CXCL10 by neurons, microglia and astrocytes, and its receptor CXCR3, expressed by neurons and microglia." (PMID 36869375, 2023). "To examine the translational potential of using a PARP-1 inhibitor to treat the sequelae of hyperglycemia in humans, we used the NCI-H716 enteroendocrine cell line that is widely used to study human GLP-1-secretion, an important modulator of insulin production." (PMID 29392078, 2018). "It is of interest to note that hyperglycaemia-induced ROS generation activates NF-κB proinflammatory pathway and the nuclear enzyme poly(ADP-ribose) polymerase-1, which in turn increases the levels of proinflammatory cytokines, cell adhesion molecules, and iNOS." (PMID 30046380, 2018). "The mechanism by which pop-1 mediates this effect remains unclear, with further work warranted to elucidate the precise role of the TCF7L2/pop-1 homolog in rescuing hyperglycemia-induced toxicity by PARP-1 inhibition." (PMID 29392078, 2018). "PARP-1 deletion reduced hyperglycemia-induced upregulation of heart weight and the ratio of HW/BW." (PMID 27027354, 2016). "With the robust induction of PARP1 by oxidative stress, ERK and/or JNK activation under hyperglycemia and hypertension may contribute to increased PARP1 activity." (PMID 26986624, 2016). "In our experiment, HG or hyperglycemia induced cardiomyocyte apoptosis, while PARP-1 inhibition or deletion could significantly reduce the number of apoptotic cells, with downregulation of cleaved caspase-3 and caspase-9." (PMID 27027354, 2016). "PARP-1 deletion could also reduce hyperglycemia-induced inflammatory response and cardiomyocyte apoptosis in mice." (PMID 27027354, 2016). "Compared with the control mice, hyperglycemia could increase the protein expression of nitrotyrosine, with an increase of PARP-1 expression and activity in DM mice." (PMID 27027354, 2016). "Hyperglycemia could significantly increase these cytokines secretion compared with the control, while PARP-1 deletion reduce it." (PMID 27027354, 2016). "In vivo, mice with PARP1 ablation are spared from hyperglycemia-induced endothelial dysfunction." (PMID 26986624, 2016). "In addition, in a model of “hyperglycemia” in vitro (elevated extracellular glucose exposure of H9c2 cells), siRNA-mediated PARP1 depletion was found to increase the levels of phosphorylated Akt (PARP1 depletion also provided significant cytoprotective effects)." (PMID 32106627, 2020).
Hyperglycemia (continued). "Given that AMPK activity is inhibited under hyperglycemia and a high level of Ang II, both known to augment oxidative stress in ECs, we first sought to test whether phosphorylation of PARP1 Ser-177 was also decreased under these conditions with the use of the newly developed anti-phospho-PARP1." (PMID 26986624, 2016). "Hyperglycemia promotes a pro-inflammatory phenotype in microglia, including augmented number of CD11+ cells in the developing cortex, increased NF-κB and PARP1 expression and decreased IκB production." (PMID 36869375, 2023). "Hyperglycemia and hypertension impair endothelial function in part through oxidative stress-activated poly (ADP-ribose) polymerase 1 (PARP1)." (PMID 26986624, 2016). "Our studies suggest a novel mechanism by which the PARP-1 inhibitor, Olaparib, effectively enhances GLP-1 activity in the setting of hyperglycemia and could represent an alternative therapeutic avenue to that of DPP-IV inhibition for T2D." (PMID 29392078, 2018). "Collectively, these studies suggest that PARP-1 inhibition may offer a novel avenue to ameliorate the negative cellular and animal effects of hyperglycemia." (PMID 29392078, 2018). "Given that PARP-1, as a potential drug target, is also conserved between C. elegans and humans, we investigated the mechanism by which PARP-1 inhibition could influence the negative effects of hyperglycemia in the C. elegans model animal." (PMID 29392078, 2018).
non-small cell lung carcinoma (29 papers, 2013 to 2025). A group of at least three distinct histological types of lung cancer, including non-small cell squamous cell carcinoma, adenocarcinoma, and large cell carcinoma. "PARP1 has been shown to promote EGFR-TKI resistance in non-small cell lung cancer through the PI3K/AKT pathway." (PMID 40713706, 2025). "In non-small cell lung carcinoma cells, PARP-1 knockdown resulted in a reversal of EMT with an increase in epithelial markers such as β-catenin, and a prominent decrease in mesenchymal markers such as vimentin." (PMID 39201718, 2024). "A previous study has shown that the suppression of FGL1 inhibits the expression of caspase 3 and PARP1, thereby enhancing the inhibitory and apoptosis-inducing activities of gefitinib in the non-small cell lung cancer (NSCLC) cell line PC9/GR." (PMID 35776395, 2022). "Studies have shown that PARP1 and DNMTs have shown an unexpected benefit in the combined treatment of non-small cell lung cancer (NSCLC)." (PMID 34149432, 2021). "Emerging evidences have demonstrated that PARP-1 overexpression leads to chemoresistance to cisplatin in non-small cell lung carcinoma." (PMID 33158052, 2020). "It is known that CIS can elicit chemoresistance through hyper activity of PARP-1 in non-small cell lung carcinomas and that PARP-1 regulates EMT through SNAIL expression in doxorubicin-resistant MDA-MB-231 cells." (PMID 31861131, 2019). "PARP-1 overexpression stimulated cell migration 2- to 3-fold in non-small cell lung cancer cells." (PMID 39201718, 2024). "DNA damage repair proteins: BLM, BRCA-1 and PARP-1 expression decreased gradually.LYY-35 can inhibit the proliferation of non-small cell lung cancer A549 cells, block cell cycle, promote apoptosis, increase ROS production, cause DNA damage and interfere with DNA replication." (PMID 38947387, 2024). "and verified the promoting effect of PARP1 gene on the migration of non-small cell lung cancer." (PMID 29152079, 2017). "For example, HIF-1α mediates the overexpression of PARP-1, XPA, and XPD, which subsequently leads to the resistance of cisplatin in non-small cell lung cancer (NSCLC) and testicular germ cell tumors." (PMID 36551540, 2022). "Compared to non-small cell lung carcinoma (NSCLC), PARP1 protein level was higher in small cell lung cancer (SCLC), leading to higher sensitivity of SCLC to PARP1 inhibitors." (PMID 28991194, 2017).
atherosclerosis (28 papers, 2009 to 2025). A disease characterized by the build-up of fatty material and calcium deposition in the arterial wall resulting in partial or complete occlusion of the arterial lumen. "Accordingly, excessive PARP‐1 activity has been associated with several tumors and inflammation‐related clinical conditions, including asthma, sepsis, arthritis, atherosclerosis, and neurodegenerative diseases." (PMID 38572951, 2024). "The present study is a direct continuation of our ongoing investigation of the role of PARP-1 in atherosclerosis and associated pathologies." (PMID 19823587, 2009). "In the present study, we used an integrative approach to assess the role of PARP-1 in the pathogenesis of atherosclerosis-associated vascular dysfunction and to investigate the effect of PARP-1 gene knockout on autonomic function and endothelium dysfunction." (PMID 19823587, 2009). "Furthermore, excess of PARP-1 activity has been associated with many tumors and inflammation-related clinical conditions, including asthma, sepsis, arthritis, atherosclerosis, and neurodegenerative diseases, to name a few." (PMID 31877876, 2019). "In atherosclerosis, the activation of PARP1 can promote the infiltration of inflammatory cells and the formation of foam cells, exacerbating the progression of atherosclerosis." (PMID 41460301, 2025). "PARP inhibition or genetic deletion of PARP1 alleviates the symptoms of atherosclerosis by reducing plaque area, lipid deposition, inflammation, and the HDL/LDL ratio." (PMID 32029456, 2020). "Second, pharmacological inhibition of PARP-1 in atherosclerosis attenuates plaque development in ApoE-/- mice." (PMID 31019462, 2019). "PARP-1 inhibition has been shown to be beneficial in a milieu of animal models of inflammatory diseases, such as diabetes, asthma and atherosclerosis." (PMID 24202328, 2013). "In order to verify that PARP-1 gene deletion protects against plaque formation in a murine model of atherosclerosis, aortas were collected from ApoE−/− or DKO mice after a 16-week regimen with regular (RD) or high-fat (HF) diet." (PMID 19823587, 2009). "Our laboratory recently demonstrated that poly-ADP-ribose polymerase (PARP)-1 is activated within atherosclerotic plaques in an animal model of atherosclerosis." (PMID 19823587, 2009). "PARP1 inhibition or KO Apoe/-e mice: ↓Plaque formation ↓Progression of atherosclerosis." (PMID 40722879, 2025). "In cardiovascular diseases, PARP1 is a core regulatory factor, which drives atherosclerosis and vascular remodeling by regulating the phenotypic transformation of vascular smooth muscle cells, and leads to myocardial hypertrophy and fibrosis by promoting inflammatory response." (PMID 41460301, 2025). "Recently, a study of atherosclerosis showed that laminar flow protected ER stress-induced cleaved forms of PARP-1 and caspase-3 and inhibited the ER stress-induced p-eIF2α, ATF4, CHOP, spliced XBP-1, ATF6, and JNK pathways to protect endothelial cells from apoptosis." (PMID 31506423, 2019). "In SMCs and endothelial cells, hyperactivation of PARP-1 by uncontrolled oxidative DNA damage could trigger a cellular energy crisis and irreversible cell death, which involved the pathogenesis of atherosclerosis." (PMID 29184509, 2017). "Inhibition of PARP-1 might shed light on the treatment of HMGB1 involved inflammation during atherosclerosis." (PMID 25793984, 2015). "Inhibition of PARP-1 may shed light on the treatment of HMGB1 involved inflammation during atherosclerosis." (PMID 25793984, 2015). "PARP-1 inhibition may also have a major impact on endothelial function, foam cell formation, lipid metabolism and the induction of cell death (switch from necrosis to apoptosis), all of which are central to the pathogenesis of atherosclerosis." (PMID 31019462, 2019). "Thus, PARP1 as a transcription factor may regulate arginase II expression and vascular endothelial function in the development of atherosclerosis." (PMID 30158868, 2018).
atherosclerosis (continued). "Reduces LDL-C, MDA and IL-6 levels; increases NO and eNOS levels; decreases plaque area in the aortic lumen of mice; improves lipid deposition; down-regulates PARP1, ARG2 and iNOS expression in mouse aortic tissue; and slows down atherosclerosis." (PMID 35566359, 2022). "Thus, PARP1 may offer a novel and promising therapeutic target for atherosclerosis." (PMID 30158868, 2018). "ROS increase activates poly(ADP-ribose) polymerase 1 (PARP-1), enzyme involved in chromatin structure modulation and DNA repair, which increases VSMC and endothelial cell death, facilitating atherosclerosis progression." (PMID 25566542, 2014). "Thus, inhibition of PARP1 may represent a promising therapeutic target in atherosclerosis." (PMID 22330242, 2012). "Oxidative damage to DNA in atherosclerosis also modifies other biochemical and regulatory pathways such as the overexpression of poly(ADP-ribose) polymerase (PARP-1)." (PMID 22330242, 2012). "Furthermore, genetic ablation of PARP1 or administration of a PARP1 inhibitor (e.g., PJ-34 and TIQ-A) to ApoE-/- mice, led to decreased atherosclerosis, which suggests an atherogenic role for PARP1." (PMID 26986624, 2016). "However, SIRT1 also activates other components of the BER pathway, including the enzymes thymine DNA glycosylase, apurinic/apyrimidinic endonuclease 1, and poly(ADP-ribose) polymerase 1,48,49 which may partly explain the profound effect of VSMC SIRT1 knockout in atherosclerosis." (PMID 29643057, 2018).
cardiac hypertrophy (27 papers, 2012 to 2025). "SUMO1 knockdown reversed PARP1 inhibitors-caused amelioration of cardiac hypertrophy in PE-treated NRCMs, as revealed by the increased protein level of ANF, increased ANF and BNP mRNA levels, and the increased cell surface area." (PMID 35002525, 2022). "Several studies have suggested that PARP-1 is closely associated with the development of cardiac hypertrophy." (PMID 34776960, 2021). "PARP-1 activity was found to be significantly upregulated in various animal models of pathological cardiac hypertrophy, and PARP-1 deficient mice significantly attenuated AngII-mediated cardiac hypertrophy." (PMID 32139662, 2020). "We found that PARP1 overexpression caused significant cardiac hypertrophy and fibrosis, as evaluated by gross morphologic examination, echocardiography, HE staining, Masson staining, WGA staining, the increased ratios of HW/BW and LVW/BW, as well as the increased protein levels of ANF and BNP." (PMID 35002525, 2022). "In addition, studies have shown that treatment with PARP-1 inhibitor (L-2286) can significantly reduce cardiac hypertrophy caused by isoproterenol (ISO)." (PMID 32139662, 2020). "Inhibiting PARP1 in diabetic mice reduced cardiac hypertrophy, fibrosis, and improved cardiac function, suggesting a protective effect against DCMY45." (PMID 40628905, 2025). "Angiotensin II-treated heart muscles of diabetic mice showed elevated PARP1 activity, cardiac hypertrophy, and inflammation, conditions which were reversed by PARP1 inhibition." (PMID 38396891, 2024). "Recent studies have supported an interaction between SIRT3 and PARP‐1 in chronic disorders, such as cardiac hypertrophy and diabetic retinopathy." (PMID 39215404, 2024). "PARP-1 contributes to caspase-independent myocyte cell death during heart failure while knockdown of PARP-2 protects against cardiac hypertrophy via SIRT1 activation." (PMID 37219631, 2023). "It has been shown that, by interacting with PARP1, SIRT3 inhibits the acetylation of PARP1, thereby reducing the activity of PARP1 to inhibit cardiac hypertrophy." (PMID 37834477, 2023). "Further evidence indicated that depletion of PARP1/ARTD1 (with genetic deletion or PJ-34 administration) in infected mice prevented cardiac hypertrophy and left ventricle dysfunction and restored the mitochondrial antioxidant/oxidant balance." (PMID 37513811, 2023). "The present work demonstrates the first time that the aggravating role of PARP1 in cardiac hypertrophy is partially attribute to its upregulation of C/EBPβ protein." (PMID 35002525, 2022). "PARP1 activity is enhanced in the progression of cardiac hypertrophy, while silencing or inhibition of PARP1 alleviates cardiac hypertrophy." (PMID 35002525, 2022). "Which is the first time to demonstrate C/EBPβ is at least partially participate in PARP1-initiated cardiac hypertrophy." (PMID 35002525, 2022). "Taken together, we have the first time demonstrated C/EBPβ PARylation inhibits C/EBPβ SUMOylation, and SUMO1 is indispensable in PARP1-induced cardiac hypertrophy because of its regulation of C/EBPβ SUMOylation and subsequent C/EBPβ protein stability." (PMID 35002525, 2022). "The results above have shown C/EBPβ PARylation inhibits its SUMOylation at K134 site, SUMO1 and PARP1 play opposite roles during the process of cardiac hypertrophy depends on C/EBPβ K134 SUMOylation and PARylation." (PMID 35002525, 2022). "It was reported that PARP-1 expression is significantly elevated in the onset and progression of cardiac hypertrophy." (PMID 34776960, 2021). "Our results suggested that quercetin protected mitochondrial function by modulating SIRT3/PARP-1 pathway, contributing to the inhibition of cardiac hypertrophy." (PMID 34776960, 2021). "Recent studies have shown that sirtuin 3 (SIRT3)/poly (ADP-ribose) polymerase-1 (PARP-1) pathway modulation inhibits cardiac hypertrophy." (PMID 34776960, 2021).